BCL2A1 (BCL2 related protein A1)
Diseases named in the same sentence as BCL2A1 in open-access papers (continued):
Sharing a sentence is not in itself a finding about the gene and the disease.
myeloid leukemia (2 papers, 2012 to 2025). A clonal proliferation of myeloid cells and their precursors in the bone marrow, peripheral blood, and spleen. "In a murine model, similar to other anti-apoptotic proteins, BCL2A1 expression has recently been shown to accelerate the onset of myeloid leukemia induced by MYC over-expression." (PMID 23118966, 2012). "BCL2A1, an anti-apoptotic protein, is not primarily associated with brain cancer metastases but plays a role in lymphoid and myeloid leukemia development." (PMID 40739397, 2025). "In myeloid leukemias, PU.1 and BCL2A1 expression are highly correlated." (PMID 23118966, 2012).
Obesity (2 papers, 2022 to 2023). Accumulation of substantial excess body fat. "Among them, the upregulated gene BCL2A1 is common in CVD, HTN, obesity, and aging; RNF144B and PTGIS are common in HCL, obesity, aging, and CVD; G0S2, CXCL1, ACKR3, and PTPRD are found in HTN, aging, and CVD; TGFB2, CA12, and MSR1 are familiar in obesity, aging, and CVD." (PMID 36035865, 2022).
psoriasis (2 papers, 2012 to 2025). An autoimmune condition characterized by red, well-delineated plaques with silvery scales that are usually on the extensor surfaces and scalp. "The differential expression analysis identified several upregulated differentially expressed genes, including OSM, CXCL8, TREM1, CXCL1, CSF3R, BCL2A1 and CXCL2, in relapsed psoriasis skin compared with baseline lesional skin." (PMID 40181552, 2025).
Stroke (2 papers, 2021 to 2023). Sudden impairment of blood flow to a part of the brain due to occlusion or rupture of an artery to the brain. "Calcium signaling pathway-related genes (AC079305.10, BCL10, BCL2A1, BRE-AS1, DYNLL2, EREG, and PTGS2) are related to apoptosis after stroke, whereas posttranscriptional regulation of BCL2A1 may be possibly associated with IS." (PMID 34987704, 2021).
thalassemia (2 papers, 2021 to 2025). An inherited blood disorder characterized by a decreased synthesis of one of the polypeptide chains that form hemoglobin. "According to their findings, the ALKBH5-mediated alteration of the m6A methylation status of BCL2A1 contributes to the pathogenesis of α-thalassemia." (PMID 40940799, 2025). "When BCL2A1 levels diminish during erythroid development, further erythrocytes production ceases, thereby aggravating thalassemia." (PMID 34650160, 2021). "Interestingly, the transcript of the anti-apoptotic protein BCL2A1 was downregulated in thalassemia patients." (PMID 40940799, 2025). "Therefore, in HbH Constant Spring α-thalassemia, apoptosis remains uninhibited as a result of the decreased expression of the BCL2A1, eventually leading eventually to hemolytic anemia." (PMID 40940799, 2025). "Lastly, we proposed involvement of m6A-regulated BCL2A1 in the pathogenesis of thalassemia." (PMID 34650160, 2021).
astrocytomas (1 paper, 2024). "By using quantitative RT‐PCR and immunohistochemistry assay, a study revealed that patients with astrocytomas and oligoastrocytomas showed high BCL2A1 expression and poor seizure control." (PMID 38641945, 2024).
Autoimmunity (1 paper, 2016). The occurrence of an immune reaction against the organism's own cells or tissues. "To further explore this problem, we study here the effects in the development of autoimmunity of the T-cell overexpression of BCL2A1 (also termed A1 or Bfl-1), another prosurvival member of the BCL2 family that together with MCL1 belongs to a different phylogenetic group than BCL2 and BCLXL." (PMID 27433938, 2016).
endometrial cancer (1 paper, 2018). Primary or metastatic malignant neoplasm involving the endometrium (mucous membrane that lines the endometrial cavity). "Ectopic expression of LRIG2 downregulated the pro-survival BCL-2 family members, including MCL-1, BCL-xL, BCL2A1, and BCL-2, whereas the pro-apoptotic BCL-2 family members, such as BAK, BAX, and BAD, were upregulated by LRIG2 in endometrial cancer cells." (PMID 29358688, 2018).
gonococcal infection (1 paper, 2024). "This hypothesis is supported by studies from multiple groups showing that anti-apoptotic factors, including BCL2A1 (Bfl-1), BIRC3 (c-IAP-2), and PTGS2 (Cox-2), are upregulated upon gonococcal infection of epithelial monolayers lacking ciliated cells." (PMID 38704381, 2024).
Granuloma (1 paper, 2021). A compact, organized collection of mature mononuclear phagocytes, which may be but is not necessarily accompanied by accessory features such as necrosis. "Our results demonstrate that BCL2A1 staining improved delineation of LCH granulomas compared to CD1a staining." (PMID 35127485, 2021). "In LCH granulomas, we uncovered the strong expression of BCL2A1 (alias BFL1), an anti-apoptotic BCL2 family member." (PMID 35127485, 2021). "Hence, LCH granulomas were better highlighted through BCL2A1 staining rather than CD1a expression in both mononucleated cells and in MGCs (asterisk)." (PMID 35127485, 2021).
gynecological cancer (1 paper, 2021). "Among apoptosis pathway components, BCL2A1, one of the hypoxia-responsive genes of the BCL2 family, was found to be significantly induced by 5.5-fold in hypoxia-treated gynecological cancer cells." (PMID 34572804, 2021).
mesothelioma (1 paper, 2021). A usually malignant and aggressive neoplasm of the mesothelium which is often associated with exposure to asbestos. "Our results thus not only revealed lots of potential candidates for ATM but also unveiled a mechanism that a new ATM substrate UBQLN4 regulates apoptosis in mesothelioma by stabilizing BCL2A1 and BCL2L10." (PMID 34245648, 2021). "Taken together, we uncover that about fifty potential substrates for ATM and clarify the mechanism that UBQLN4 inhibits the apoptosis in mesothelioma by phosphorylating the site of Ser318 and stabilizing BCL2A1 and BCL2L10." (PMID 34245648, 2021). "Phosphorylated UBQLN4 prevented cytochrome c release and inhibited apoptosis in mesothelioma during DNA damage by stabilizing BCL2A1 and BCL2L10." (PMID 34245648, 2021). "Furthermore, UBQLN4 inhibits the apoptosis in mesothelioma by stabilizing BCL2A1 and BCL2L10." (PMID 34245648, 2021). "All three proteins, UBQLN4, BCL2A1, and BCL2L10, were highly expressed in all cases of mesothelioma tissues." (PMID 34245648, 2021). "Our further study demonstrated that UBQLN4 acts as an anti‐apoptotic factor, which interacts with and stabilizes the anti‐apoptotic proteins BCL2A1 and BCL2L10, and regulates mesothelioma cell apoptosis in response to DNA damage." (PMID 34245648, 2021). "In this study, we not only identified UBQLN4 as a substrate for ATM, but also found that UBQLN4 interacts with and stabilizes the anti‐apoptotic proteins Bcl‐2‐related protein A1 (BCL2A1) and Bcl‐2‐like protein 10 (BCL2L10) and prevents mesothelioma cell apoptosis in response to DNA damage." (PMID 34245648, 2021). "Immunohistochemistry assays indicated that BCL2A1 and BCL2L10 are highly expressed in mesothelioma." (PMID 34245648, 2021). "Besides, we found that the depletion of BCL2A1 and BCL2L10 could enhance the sensitivity to the treatment of CPT in mesothelioma cells." (PMID 34245648, 2021). "Therefore, we further investigated the anti‐apoptotic mechanisms of BCL2A1 and BCL2L10 in mesothelioma and found that UBQLN4 could prevent MOMP in mesothelioma cells with CPT treatment." (PMID 34245648, 2021).
metastatic disease (1 paper, 2014). "In summary, BCL2A1 has been identified as overexpressed in a variety of haematological malignancies as well as solid tumours and appears to be predominantly associated with advanced or metastatic disease stages." (PMID 26556430, 2014).
nasal polyps (1 paper, 2021). "Our study has proved the increased expression of ALOX5AP, BCL2A1, BTK, CYBB, NCF2, HCK, and HK3 by mRNA and protein levels in nasal polyps." (PMID 33603773, 2021). "We found that ALOX5AP, BCL2A1, BTK, CYBB, NCF2, HCK, and HK3 were broadly expressed on both epithelial layer and stromal layer in nasal polyp tissues." (PMID 33603773, 2021). "Next, we identified the protein level of the seven hub genes (ALOX5AP, BCL2A1, BTK, CYBB, NCF2, HCK, and HK3) from nasal polyps from CRSwNPs and nasal mucosa from healthy controls." (PMID 33603773, 2021). "Moreover, the immunohistochemistry stain results also demonstrated that the protein level of ALOX5AP, BCL2A1, BTK, CYBB, NCF2, HCK, and HK3 were significantly increased in nasal polyps compared to control subjects." (PMID 33603773, 2021).
osteosarcoma (1 paper, 2025). A usually aggressive malignant bone-forming mesenchymal neoplasm, predominantly affecting adolescents and young adults. "ELK1 activation was also reported to control anti-apoptotic Bcl-2-related protein A1 (BCL2A1) expression in osteosarcoma cells, in a 2014 study." (PMID 40862737, 2025).
ovarian tumors (1 paper, 2021). "In two pairs of patient samples (P15 and P21), the analysis indicated that the relative expression of BCL2A1 after normalization by β-actin was 1.6–3.7-fold higher in metastatic ovarian cancer cells isolated from lavage/ascites than in those from the paired primary ovarian tumors." (PMID 34572804, 2021).
pulmonary fibrosis (1 paper, 2024). Chronic progressive interstitial lung disorder characterized by the replacement of the lung tissue by connective tissue, leading to progressive dyspnea, respiratory failure, or right heart failure. "We speculate that the mechanism of MCL-1 and BCL2A1 participating in promoting pulmonary fibrosis is related to apoptosis resistance." (PMID 38609879, 2024).
schizophrenia (1 paper, 2024). A major psychotic disorder characterized by abnormalities in the perception or expression of reality. "Bcl-2 family proteins,including BCL2A1, are known to regulate the balance between cell survival and programmed cell death.In schizophrenia, BCL2A1 upregulation in the prefrontal cortex is linked to grey matter loss, which has been associated with cognitivedeficits." (PMID 40162448, 2024). "The highlight of this study was the identification of four key genes associated with schizophrenia: significant upregulation ofS100A8, S100A9 and BCL2A1 and downregulation of CBLB." (PMID 40162448, 2024). "The upregulation of BCL2A1 in our study underscores the importance of apoptosis regulation in schizophrenia." (PMID 40162448, 2024). "Interestingly, BCL2A1's dual role in either promoting or inhibiting apoptosis depending on the cellular context suggests a complexregulatory mechanism in schizophrenia." (PMID 40162448, 2024). "This study identified key molecular changes in schizophrenia, notably the upregulation of S100A8, S100A9 and BCL2A1 and thedownregulation of CBLB, highlighting the involvement of neuro-inflammatory pathways, apoptosis regulation and immune modulation in thedisease." (PMID 40162448, 2024).
serous ovarian cancer (1 paper, 2021). "The survival analysis showed that patients with serous ovarian cancer with increased BCL2A1 copy numbers had a lower survival probability with a hazard ratio of 1.672 and a log-rank test p-value of 0.10." (PMID 34572804, 2021). "A highly tumorigenic high-grade serous ovarian cancer cell line, OVCA433 cells, was selected for depleting BCL2A1 by the CRISPR/Cas9 knockout system." (PMID 34572804, 2021).
virus infection (1 paper, 2014). "It is interesting to point out that Bcl-2 is an important anti-apoptotic factor and, like Bcl2A1, helps KSHV infection bypass apoptosis, an important barrier inherent in virus infection, as well as autophagy, a pathway well-known to antagonize KSHV infection." (PMID 25340789, 2014).
cancer (90 papers, 2011 to 2025). A tumor composed of atypical neoplastic, often pleomorphic cells that invade other tissues. "Prior findings of viral gene anticorrelation with MYC, STAT3, and BCL2A1 and lytic cell upregulation of cancer-associated stem-like pluripotency and host shutoff escapees were conserved in B958-ZHT." (PMID 38915538, 2024). "BCL2A1 has been shown to be overexpressed in many cancers and is associated with resistance to chemotherapeutic and targeted drugs." (PMID 37889551, 2023). "Our analysis also showed an increase in BCL2A1, an anti-apoptotic player, usually implicated in cancer progression." (PMID 31717414, 2019). "This prediction could be validated assessing, for example, the cellular protein levels of the corresponding Bcl2a1 variants and their propensity for increased degradation by the proteasome, as recently shown for other cancer mutations." (PMID 31825969, 2019). "BCL2A1 is tightly regulated in normal tissues but often overexpressed in cancers such as AML, CLL, DLBCL, breast cancer, melanoma, and lung cancer." (PMID 41155156, 2025). "BCL2A1 overexpression induces a protumorigenic and chemoresistant function in malignant cells and represents an attractive target in cancer." (PMID 41295250, 2025). "B-cell lymphoma 2-related protein A1 (BCL2A1), a highly regulated NF-κB target gene, is known for its pro-survival roles in the hematopoietic system and is overexpressed in various cancers, contributing to tumor progression." (PMID 40110037, 2025). "In the baseline samples, high expression of anti-apoptotic genes MCL1 and BCL2A1 in MDSCs from patients with cancer was observed compared with other cell types." (PMID 40762981, 2025). "Particularly in the context of resistance to current therapies, BCL2A1 appears to play an important role in protecting cancer cells from the induction of cell death." (PMID 39192247, 2024). "To investigate BCL2A1 mRNA expression across cancers, we downloaded RNA-seq data for 33 types of tumor tissues and normal tissues from the TCGA and GTEx datasets." (PMID 37889551, 2023). "It has been proven that persistent VTX exposure leads to the upregulation of different pro-survival Bcl-2 family members, such as BCL-XL, MCL-1, and BCL2-A1, which have been found to be overexpressed in many hematologic malignancies and other cancers." (PMID 38069030, 2023). "The level of BCL2A1 is enhanced in different types of cancer cells, resulting in tumour progression and chemotherapy resistance." (PMID 35804353, 2022). "In our study, the expression of BCL2 and BCL2A1 in the differential hypermethylation pathway was down-regulated in A549 cancer cell line compared with normal lung epithelial cells." (PMID 34308964, 2021). "BCL2A1 is an apoptosis modulator that is overexpressed as a nuclear factor kappa B target gene in many cancer cells and contributes to tumor progression." (PMID 33626234, 2021). "For the quantification of PD-L1 expression (biomarker in cancer immunotherapy), CCL18, TNFAIP6, and BCL2A1 had higher diagnostic efficiency (AUC > 0.7)." (PMID 35265629, 2021). "Overexpression of BCL2A1 in cell lines has been found to promote resistance to different cancer drugs including the BH3 mimetic ABT-737, a specific inhibitor targeting Bcl-2, Bcl-xL, and Bcl-w." (PMID 31825969, 2019). "EGFR, ERBB3, MMP20, MMP27, MCL1, BCL2A1 and BAK1 appear to be important genes for cancer progression due to their frequent association with recurrent cancer-related genes in women." (PMID 31205821, 2019). "A potential limitation for our prediction model extends to cancers with high expression of BCL2A1 or BCL-W." (PMID 28714472, 2017). "For example, SFRP4, WNT11, FZD2, MYC were highly expressed in cancer tissues which represent the Wnt pathway was activiated and BCL2A1, ICM1, TNFSF14 in NF-κB pathway were highly expressed as well." (PMID 25928635, 2015). "Various cancers such as gastric stomach, colon, and breast have been shown to have elevated levels of BCL2A1." (PMID 26036629, 2015).
cancer (continued). "Conversely, silencing BCL2A1 sensitizes T or B cancer cells to apoptosis induced by chemotherapy or anti-CD19 biotherapy, in both cell lines and cells from patients." (PMID 23441221, 2013). "However, BCL2A1 is a potential target in cancer therapy, and inhibitors of this protein are developing." (PMID 38214842, 2024). "Analysis of the potential correlation between the expression of 5 core protein coding genes and drug sensitivity in different human cancer cell lines from CellMiner database, which showed that the expression of BCL2A1 was positively correlated with the drug sensitivity of Vemurafenib." (PMID 36524001, 2022). "To further determine whether CCL18 and BCL2A1 could be used as predictive biomarkers for cancer immunotherapy, such as cisplatin IC50, we investigated their relationship with hallmarks of genomic instability (biomarkers for immunotherapy)." (PMID 35265629, 2021). "According to previous reports on BCL2A1 functions in different cancer cells or normal cells, it was hypothesized that BCL2A1 could augment the capability to resist stress-induced cell apoptosis." (PMID 34572804, 2021). "Considering that the main BCL2A1 function is to control the release of cytochrome c from mitochondria in the intrinsic apoptotic pathway, it may be an attractive target for anti-cancer therapies." (PMID 34833004, 2021). "Besides, both CCL18 and BCL2A1 were significantly related to the occurrence and development of cancer." (PMID 35265629, 2021). "The four reported cancer mutations in Bcl2a1, M75R, L99R, Y120C and, V145L are not located in the proximity of the BH3-binding domain and are not predicted to have any local effects on the complex formation." (PMID 31825969, 2019). "We further validate that splicing modulator induces selective apoptosis in cancer cell lines with endogenous amplification and high expression of MCL1 or BCL2A1, and combination of splicing inhibition and BCLxL (encoded by BCL2L1) inhibition induces a synergistic cytotoxicity in cancer cells." (PMID 30635584, 2019). "By inducing the ubiquitination and degradation of the pro-survival factor BCL2A1, TRIM28 may have an anti-tumoral activity in cancer cells whose survival depends on a high expression of BCL2A1." (PMID 30974870, 2019). "Thus, human BCL2A1 is overexpressed in a variety of cancer cells, including hematological malignancies and solid tumors and contribute to tumor progression." (PMID 23441221, 2013). "Cancer cells can evade MCL1 inhibition by upregulating untargeted pro-survival BCL2 family members, particularly BCLXL and BCL2A1, enabling continued survival despite MCL1 blockade." (PMID 41155156, 2025). "Increased expression of BCL2 family members including MCL1, BCL2L1 (BCL-xL), BCL2A1 (BFL1), and BCL2 itself drives resistance to single-agent venetoclax in various cancers." (PMID 39894894, 2025). "In response to venetoclax-induced pressure, cancer cells often shift their apoptotic dependencies by increasing expression of MCL1, BCLXL, or BCL2A1." (PMID 41155156, 2025). "We also investigated the dependency profile of BCL2 family proteins (BCL2, BCL2L10, BCL2A1, BCL2L1, and MCL1) in GBM within Cancer Cell Line Encyclopedia, and found that GBM cells show the greatest dependency on Bcl-xL (BCL2L1) for survival." (PMID 38383492, 2024). "BCL2A1 and c-MYC are both described to be relevant for cancer cell survival and additionally seem to correlate in a c-MYC overexpression context, indicating similar regulation of both genes and shared upstream signaling pathways." (PMID 39192247, 2024). "Among the five antiapoptotic genes, three (BCL2, BCL2A1, and MCL1) can be regulated by NF-κB in different types of cancer cells." (PMID 36853387, 2023). "Among them, KRT7 was highly expressed in cancer cells, AEBP1 was mainly expressed in fibroblasts, BCL2A1 and RGS1 were both highly expressed in myeloid cells." (PMID 37996875, 2023).